LUM (lumican)
Diseases named in the same sentence as LUM in open-access papers (continued):
Sharing a sentence is not in itself a finding about the gene and the disease.
tumor (continued). "Importantly, GB-induced CMA in murine PCs has been shown to increase the secretion of molecules such as Osteopontin (OPN), which supports tumor growth, while the inhibition of this CMA upregulation leads to the release of molecules with anti-tumor properties, such as Lumican." (PMID 39796053, 2024). "Thus, the AC117386.2/hsa-miR-378c/LUM regulatory axis may be the most likely mechanism in mediating STAD tumor stage progression." (PMID 38129820, 2023). "Therefore, LUM protein expression in these tumor tissues may be higher than LUM expression in normal tissues." (PMID 37692065, 2023). "Besides, our data show potential biomarkers for good GB prognosis such as lumican and vitamin D in the identified subset of the CMA-deficient PC secretome with GB, including proteins related to anti-tumor mechanisms and immune responses." (PMID 35419364, 2022). "Therefore, lumican repressed tumor growth in this model, increasing endothelial cell apoptosis." (PMID 34572532, 2021). "Notably, lumican was shown to be a strong endogenous inhibitor of tumor growth." (PMID 33917849, 2021). "Furthermore, we studied the co-expression network of LUM and found that LUM could promote tumor metastasis and invasion." (PMID 33493133, 2021). "The role of lumican on tumor progression may be divided into several parts." (PMID 31963522, 2020). "Thus, lumican was able to modulate the response of a therapeutic peptide targeting the extracellular matrix by specific inhibition of thrombospondin-1, playing a substantial role in maintaining tumor microenvironment integrity." (PMID 32548117, 2020). "Hence, LUM expression contributes to migration and metastasis formation in a tumor-specific manner." (PMID 31861249, 2019). "Interestingly, our data show that lumican expression within host tissues affects both soluble factors as well as immune and endothelial cells intratumoral distribution, hence sharply modifying tumor response to TAX2 peptide." (PMID 28794454, 2017). "Moreover, it is unknown what proportion of secreted lumican and versican is locally captured by the (tumor) tissue and still can be visualized by immunohistochemistry." (PMID 28481899, 2017). "Hence, we sought to determine whether the impact of lumican on tumor ECM topology may depend on collagen fibrillogenesis." (PMID 28794454, 2017). "Interestingly, TAX2 inhibitory effects regarding these vascularization parameters appeared even larger in Lum−/− mice as compared to those observed in WT mice, therefore demonstrating an influence of lumican host expression on tumor inhibitory anti-angiogenic response." (PMID 28794454, 2017). "Therefore, ongoing studies are now aimed at further deciphering the pathway involved, as well as to investigate a putative role for lumican in fostering tumor response to immunotherapeutic approaches such as immune checkpoint inhibitors anti-PD-1 and anti-CTLA-4." (PMID 28794454, 2017). "Thus, it may be highly relevant to gain deeper insights about lumican-related modifications of matrix assembly that may impact tumor growth and/or dissemination." (PMID 28794454, 2017). "Similarly to DCN, LUM is reported to mediate tumor suppression." (PMID 26230845, 2015). "Multivariate logistic regression was performed to correct for dependency between independent predictors of outcome and to investigate whether lack of versican and lumican expression in the tumor were independent risk factors for disease recurrence." (PMID 22711178, 2013). "Meanwhile, Domain 4 expressed tumor-suppressive genes like DCN, LUM, BGN, and COL1A2, suggesting a protective microenvironment." (PMID 40838787, 2025).
tumor (continued). "Using three spatially-enriched marker genes for each tumor subregion (CT: BCAN, CSPG5, TOP2A; Pseudo: HILPDA, IGFBP5, LGALS3; and MVP: MGP, LUM, THBS1) we identified distinct sub-populations of malignant cells from the scRNA-seq data." (PMID 41366031, 2025). "In comparison to tumor vasculature in MVP and CT regions, SLIT3, COL8A1, LUM and POSTN showed enhanced spatial enrichment within the GBM hyperplastic region." (PMID 41366031, 2025). "CSR‐related genes (COL1A1, LOXL2, LUM, FN1, and TGFB1) reflect extracellular matrix deposition and stromal activation, hallmarks of invasive tumor behavior." (PMID 41407509, 2025). "Decorin (DCN) and lumican (LUM), which are involved in the regulation of COL fibril assembly and stability, had high abundances in both NAT and tumor tissues; but their levels were much higher in NAT tissue than in tumor tissue." (PMID 40032993, 2025). "Parietal peritoneal thickening showed the overexpression of LUM, MMP11, and DUSP1 in the tumor region, MMP11 and CTSK in the stromal region, and MMP11 and CTSK in the immune region (adjusted p-values ≤ 0.002)." (PMID 39135097, 2024). "The expression of chemoresistance genes has been detected, including KLF4 (doxorubicin and ifosfamide), ULK1, LUM, GPNMB, and CAVIN1 (doxorubicin), and AHNAK2 (gemcitabine) in tumor cells and ETS1 (gemcitabine) in TME." (PMID 39685635, 2024). "While LUM (lumican), DCN (decorin) and VASP (vasodilator stimulated phosphoprotein), that are known tumor suppressors were found to be downregulated in the EVs derived from NB patients." (PMID 38660306, 2024). "Lumcorin is a peptide derived from LUM leucine-rich repeat (LRR) domain 9, which has anti-tumour activity." (PMID 38474072, 2024). "LUM, COL18A1, BGN, PRELP, and ASPN showed increased expression in tumor tissue compared to the paired NAT tissue, inconsistent with the declined trend in other histologic subtypes." (PMID 39305996, 2024). "This functional cluster of proteins was also identified by proteins involved in proteoglycan metabolism: in addition to lumican, decorin, and mimecan, UDP-glucose 6-dehydrogenase (UDP-GlcDH) was also identified, with the lowest level in the tumor." (PMID 39195201, 2024). "Our results are supported not only by the role of Lumican and OPN in polarizing immune cells but also by a possible complementary role in the intravasation and subsequent extravasation of tumor cells in metastasis." (PMID 39796053, 2024). "LUM is an ECM matrikine that regulates multiple cellular activities and also has anti-MMP activity, anti-tumour activity and, promotes corneal epithelial wound healing, regulating gene expression maintaining corneal homeostasis." (PMID 38474072, 2024). "The tumor immune microenvironment (TIME) was examined for any difference between low and high LUM expression levels in STAD." (PMID 38129820, 2023). "CD44 marks an aggressive tumor-promoting CRC cell population and lumican (LUM) is a mesenchymal marker that is upregulated in CRC cells in collagen cultures during EMT." (PMID 37511344, 2023). "Organoid cells were identified by the expression of the tumor markers KRT18 and KRT19 whereas CAFs were characterized by DCN and LUM expression." (PMID 36273171, 2022). "LGALS1, B4GALT6, and GALNT11 were upregulated and MGAT5, MAN1A1, MANBA, LUM, GALNT1 and 7, HAPLN3, and ST6GALNAC5 were downregulated in Fra-2 cl 1 select primary tumours, while MGAT4A was upregulated." (PMID 34693476, 2022). "The presence of transcripts for FMOD, PRELP and OMD was widespread in the patients analyzed, while expression of LUM and KERA was detected in only around 50% of cases in both healthy and tumor tissue." (PMID 34440771, 2021). "However, the role of LUM in the COAD tumor microenvironment remains unclear." (PMID 33493133, 2021). "The expression of LUM and VCAN negatively correlated with tumor purity, whereas the expression of EFNA4 positively correlation with tumor purity." (PMID 34093807, 2021).
tumor (continued). "Lumican in PRKDC tissues was reported to be higher at the protein level, and further correlations between the lumican protein and tumor grading, OS, and organ and lymph node metastasis status were also found." (PMID 34977258, 2021). "This histological observation confirms the role of lumican in maintaining the ECM architecture and, thus, controlling tumor development." (PMID 34885059, 2021). "Lumican, a small leucine-rich proteoglycan (SLRP) of the extracellular matrix (ECM), displays anti-tumor properties through its direct interaction with MMP-14." (PMID 34638415, 2021). "Lumican was shown to protect collagen against MMP-14 proteolysis, leading to inhibition of tumor progression." (PMID 34638415, 2021). "In the present report, we investigated the effect of lumican on ECM organization and tumor progression in ovarian primary tumors by combining FTIR and SHG imaging with conventional histology and immunohistochemistry." (PMID 34885059, 2021). "Therefore, soluble lumican, secreted by tumor cells or released from degraded bone matrix, may induce the cytoskeleton rearrangement of tumor cells through binding to self-expressed integrin receptor, which increases cell mobility and enhances the tumor adhering with bone matrix." (PMID 31963522, 2020). "The first of the top three we identified is LUM (lumican), a glycoprotein which is involved in the extracellular matrix (ECM) formation and regulation and which can have a strong impact on the tumor microenvironnement or stroma function." (PMID 32055239, 2020). "We previously identified several key factors in mediating CAFs’ tumor-promoting properties in GC, including HGF, Lumican and IL-6." (PMID 31659258, 2020). "Several studies have shown that tumor spheroids display an enhanced deposition of tumor ECM proteins (e.g., fibronectin, lumican, laminin, and collagen type I and VI) in comparison to 2D cell culture models." (PMID 31514390, 2019). "We evaluated the colocalizations of lumican with HIF-1α and phosphorylated AMPK at the interface between cancer cells and stromal cells in patient tumor tissues." (PMID 31406961, 2019). "LUM differs from FMOD in terms of cell interactive properties, being an MMP-14 inhibitor and it impedes tumor cell migration and growth through its interaction with α2β1 integrin which conveys anti-angiogenic properties." (PMID 30700002, 2019). "In the tumor microenvironment (TME) of primary PDAC, the presence of lumican within the ECM has been positively and negatively correlated with tumor progression." (PMID 31406961, 2019). "Lumican is a class II small leucine-rich proteoglycan with a key role in ECM organization and modulation of biological functions dependent on tumor type, abundance, and stage of disease." (PMID 31406961, 2019). "Lumican (LUM) has a role in cell migration and proliferation during embryonic development, tissue repair and tumour growth through regulation of matrix metalloprotease activity and collagen fibrillogenesis." (PMID 30992697, 2019). "This leads to the conclusion that lumican expression may be increased in a more progressed disease state independent of specific tumor progression-associated chromosomal aberrations, while increased stromal versican expression may be induced by factors directly regulated by gain of chromosome 13q." (PMID 28481899, 2017). "In tumour tissues, the expression of many ECM molecules, including small proteoglycan like LUM, was observed." (PMID 29088800, 2017). "Lumican’s leucine rich repeat (LRR) motifs participate in the process of collagen assembly, control cell migration and also regulate tumor cell progression." (PMID 26930497, 2016). "All seven glucose metabolism-related proteins were downregulated in SBP1 induced-tumor tissue, including GAA, GAPDH, ALDH2, Thioredoxin, ENO3, UGDH and Lumican." (PMID 25974208, 2015). "Conversely, lumican can be degraded by MMP-14, revoking its anti-tumor properties which depend on intact native molecule." (PMID 24098450, 2013).
tumor (continued). "On the other hand, lumican (and decorin) can be degraded by MMP-14, abrogating the anti-tumour effect of these proteins." (PMID 23236386, 2012). "Immunohistochemistry showed high expression of INHBA and NEK6 proteins in 14 of 20 and 24 of 27 tumour tissues, respectively, whereas IGFBP7 and LUM proteins showed little immunoreactivity in tumour tissue relative to adjacent healthy tissue (data not shown)." (PMID 18827816, 2008). "From TCGA transcriptome differential analysis, the expression of LUM in the PDAC is much higher than tumor adjacent non-cancerous tissues." (PMID 40789825, 2025). "Lumican and OPN, as biomarkers, could be used to predict the infiltration tendency of the tumor and give information about the possible response of patients to treatments, as these proteins are related to CMA-dependent PC immune function." (PMID 39796053, 2024). "Indeed, a number of proteins within the PG score, such as LUM, HSPG2, DCN and BGN, have established tumor suppression functions in other cancer types." (PMID 38810090, 2024). "Our results confirmed that Lumican and OPN in perivascular areas of the GB peritumoral niche are effective predictive biomarkers for evaluating prognosis and monitoring possible therapeutic immune responses dependent on PCs in tumor progression." (PMID 39796053, 2024). "The findings showed that LUM expression, negatively correlated with DNAss in 10 tumor types, including STAD, LIHC and TGCT; positively correlated with DNAss in 8 tumor types, including LGG, THYM and THCA; and significantly negatively correlated with RNAss in all tumor types." (PMID 37692065, 2023). "Like LUM, TXNIP was abundant but downregulated in the analyzed tumor samples." (PMID 36982287, 2023). "In 16 cancer types (LIHC, LUAD, KIRC, OV, and UCEC), we found suppressed LUM levels in tumor tissues, relative to neighboring non-tumor tissues." (PMID 37692065, 2023). "In both groups (Fra-2 cl 1 and cl 2), some interesting genes could be identified, e.g., in the Fra-2 cl 1 primary tumours LGALS1, ADRM1, and CTTN, which were upregulated and LUM (Lumican), MAN1A1, and SPARC, which were significantly downregulated." (PMID 34693476, 2022). "Transcripts for the five genes encoding class II SLRPs (FMOD, LUM, PRELP, KERA and OMD) were quantified in both healthy and tumor tissue, with no significant expression differences between tissue type." (PMID 34440771, 2021). "To further explore the LUM-related molecules functioning in COAD, we used the LinkedOmics database to analyze mRNA /miRNA sequencing and clinical data from 105 COAD patients in the clinical proteomic tumor analysis consortium (CPTAC) database." (PMID 33493133, 2021). "Lumican is expressed in various tumor tissues, but both positive and negative correlations with tumor aggressiveness have been reported, highlighting it as either a therapeutic molecule or an anti-cancer target." (PMID 34885059, 2021). "Lumican, a small, leucine-rich proteoglycan, can directly bind to and inhibit MMP-14 and, hence, may limit tumor progression by preventing collagen degradation and invasion." (PMID 35008569, 2021). "Therefore, all those three useful prognostic indicators, LUM, VCAN, and EFNA4 are considered to have a relationship with the immunoregulation of the tumor environment." (PMID 34093807, 2021). "Altogether, both imaging and histological methods evidence that the absence of LUM leads to a loss of ECM integrity by disorganization of the collagen fiber network, potentializing edema formation and tumor progression." (PMID 34885059, 2021). "Lumican (LUM), which also increased with LV-MEIS1 expression (fold-change = 2.88, FDR = 1.79×10−9), is another member of the tumor-suppressive SLRP protein family and has been shown to increase integrin B1 (ITGB1)-mediated adhesion as well as regulate expression of ITGB1." (PMID 32553107, 2020).
tumor (continued). "Moreover, COL6A3, DCN, and LUM, which were upregulated after the WNT pulse here, are all typical markers for the switch to a mesenchymal phenotype in lens epithelial and tumor cells." (PMID 33195222, 2020). "Lumican was shown to inhibit angiogenesis in various tumors; however, the utilization of the 4T1 BC model demonstrated lumican attenuated 4T1 tumor growth and lung metastasis, but not angiogenesis." (PMID 32847060, 2020). "Finally, it was also observed that lumican decreases β1-integrin and MT1-MMP expression and prostate cancer invadopodium formation to reduce tumor invasion capability." (PMID 31052560, 2019). "In contrast, lumican was neither detected in the dermis nor in stromal cells within tumor from Lum−/− animals, therefore confirming the lumican-null phenotype." (PMID 28794454, 2017). "Immunoblotting results addressed that fibroblasts, rather than tumor cells, are a putative source for the high lumican levels recorded in AdC PEs." (PMID 25961303, 2015). "Again, lumican immunoreaction was not related to tumor grade, stage (pTNM), and vascular/pleural invasion." (PMID 25961303, 2015). "Another protein found differentially abundant in samples with the Q-profile was lumican, a member of the small leucine-rich proteoglycan family (SLRP) with important roles in embryonic development, tissue repair, tumor growth, organization of collagens and maintenance of corneal transparency." (PMID 18431506, 2008). "Decorin and lumican can suppress growth factor signaling (e.g., TGF-β and EGFR), while biglycan may promote inflammatory signaling through TLR2/4, underscoring their dual tumor-suppressive and tumor-promoting roles." (PMID 41228294, 2025). "Pro-IL-12, IL-12-MSA-Lumican, CBD-IL-12, M-L-IL-12, and NHS-muIL12 —designed based on fusion extracellular matrix or immune molecular strategies—showed good antitumor effects in preclinical tumor-bearing mice and had synergistic effects in combination with other therapies." (PMID 39451566, 2024). "Fewer than 16% (7/46) of tumor specimens displayed negative LUM expression." (PMID 38129820, 2023). "Lumican, a matrix protein which have an anti-tumor role inhibiting immune scape or even reversing several metastatic features in cancer cells was produced in all experimental conditions, but mainly by KO PC in presence of GB as CMA dependent anti-tumor protein." (PMID 35419364, 2022). "Furthermore, lumican is expressed in various cancer tissues and is reported to have a positive or negative correlation with tumor progression." (PMID 34572532, 2021). "The cell binding study was repeated using these primary tumor cell lines and showed a binding profile very similar to 786-O, with strong binding to fibronectin, collagen VI, and collagen XII and inefficient binding to or repulsion by periostin, lumican, and tenascin C." (PMID 34884982, 2021). "In a retrospective study including PDAC patients, those with lumican-positive tumor cells survived longer than those with lumican- negative cells, whereas patients with lumican-positive stromal tissue had a lower survival than those with lumican-negative stroma." (PMID 32308769, 2020). "Indeed, none of the AdCs showed a lumican immunoreaction in more than 70% of tumor cells and in only 12 cases it exceeded the 31%." (PMID 25961303, 2015). "Analysis of a large genomic patient dataset revealed that the SLRPs lumican, fibromodulin and decorin as well as COL1A1 and COL6A1 all correlate with good overall survival in SHH MB patients; suggesting that the presence of this ECM shell in SHH tumours may be a reliable biomarker of good outcome." (PMID 36631900, 2023). "Genes that encoded extracellular matrix (ECM) components, such as COL1A1, COL1A2, LUM and FN1, were specifically expressed by fibroblasts, suggesting that the ECM in the NPC microenvironment was highly complex and might interact with surrounding tumor and stromal cells via integrin signaling." (PMID 33750785, 2021).